INS (insulin)
Diseases named in the same sentence as INS in open-access papers (continued):
Sharing a sentence is not in itself a finding about the gene and the disease.
Insulin resistance (continued). "Insulin resistance, de- fined as inadequate glucose uptake by peripheral tissues, induces pancreatic -cells to produce more insulin to lower blood glucose levels to compensate for the resistance, which burdens the -cells with more stress and exacerbates their dysfunction." (PMID 40082942, 2025). "Leptin, through the glucose-stimulated insulin secretion pathway, is directly related to the secretion of insulin granules, which may promote insulin resistance." (PMID 41347218, 2025). "By targeting the AGE-RAGE and PI3K/AKT signalling pathways, GP could help to reduce insulin resistance and increase insulin production." (PMID 40894207, 2025). "Although DAPA treatment can alleviate insulin resistance and hyperinsulinemia to some extent, it may also impact insulin secretion from the pancreas, leading to a significant increase in insulin secretion overall." (PMID 40136402, 2025). "In addition, GLP-1R stimulation activates insulin signaling pathways and regulates gene expression, decreasing systemic insulin resistance and brain insulin resistance in patients with AD." (PMID 40778306, 2025). "It is well known that IL6 interferes with glucose uptake in insulin-dependent tissues, by inducing insulin resistance; therefore, it also interferes with lipolysis and oxidation of glucose and fatty acids, with a resultant loading of the adipocytes with nutrients." (PMID 40003433, 2025). "Although only SMOC2 in SAT reached statistical significance, lower gene expression across all genes was observed in individuals with insulin resistance (IR; N = 42) compared to their insulin-sensitive (IS; N = 31) counterparts, with this pattern being more pronounced in OVAT." (PMID 41275133, 2025). "Diabetic patients tend to have larger adipocytes compared to non-diabetics; insulin sensitivity is inversely related to adipocyte size, and markers of insulin resistance are significantly associated with lower HDL-C levels." (PMID 40078416, 2025). "However, in obesity-induced insulin resistance, insulin’s ability to transport intracellular potassium is impaired, leading to relative hypokalemia in the extracellular compartment." (PMID 40136609, 2025). "Thus, fewer glucose transporter proteins 4 and/or post-receptor defects in the insulin signaling cascade response lead to insulin resistance." (PMID 40660544, 2025). "Given the importance of the glycerophospholipid metabolic pathway in modulating insulin resistance, we hypothesize that aspirin may improve endometrial insulin sensitivity by regulating this pathway." (PMID 40403007, 2025). "Furthermore, EVs from obese mice induce insulin resistance when transferred to lean mice, whereas EVs from lean mice improve insulin sensitivity in obese recipients." (PMID 41347018, 2025). "However, in cases of insulin resistance or inadequate insulin secretion, this inhibitory effect diminishes, resulting in increased glycogenolysis in the liver and elevated glucose release into the bloodstream, leading to higher blood sugar levels." (PMID 40260393, 2025). "This could be attributed to the fact that a high NLR often indicates the presence of an inflammatory response, which promotes insulin resistance and necessitates higher insulin doses to maintain glycemic control." (PMID 41427046, 2025). "Furthermore, abnormal lipid metabolism, marked by increased free fatty acid levels, exacerbates insulin resistance by disrupting insulin-mediated glucose metabolism in cells." (PMID 41378205, 2025). "Similarly, in T2DM, DNA methylation affects insulin gene expression and beta cell differentiation, glucose metabolism and insulin resistance." (PMID 41220583, 2025). "Insulin resistance denotes a compromised biological responsiveness to insulin." (PMID 39136514, 2025). "While we focused on glycemic control and insulin levels, future studies on insulin sensitivity using the Homeostatic Model Assessment of Insulin Resistance (HOMA-IR) could enhance the translational value of these findings." (PMID 40283884, 2025).
Insulin resistance (continued). "If insulin resistance occurs, the insulin signaling pathway is impaired, leading to renal damage." (PMID 40416818, 2025). "Furthermore, obese ZSF-1 rats are characterized by hyperinsulinemia and insulin resistance, as well as glucose intolerance, which is supported by elevated insulin and glucose levels." (PMID 40649974, 2025). "However, it effectively improved obesity (body weight, liver/GAT weight), insulin levels, and insulin resistance in WD-induced metabolic disorder models." (PMID 41034188, 2025). "Additionally, fasting serum glucose and insulin levels were used to calculate the homeostatic model assessment for insulin resistance (HOMA-IR)." (PMID 40722894, 2025). "Therefore, the impact of perimenopause on the onset of impaired insulin response and insulin resistance needs to be further explored." (PMID 39823117, 2025). "In a study assessing CUR's impact on insulin resistance genes and GLUT- 4 in DHEA-induced PCOS rats, CUR (200 mg/kg) effectively restored normal body weight, insulin resistance, blood glucose, and serum insulin levels compared to the 100 mg/kg CUR and control groups (p < 0.05)." (PMID 40234918, 2025). "Its elevated levels in obesity may reflect a compensatory response, similar to insulin increases in insulin resistance." (PMID 41417360, 2025). "Use of the HOMA scores is undoubtedly convenient, but using improved measures of insulin resistance or insulin secretion may improve the performance of this precision approach." (PMID 39621104, 2025). "1-phosphatidylinositol-3-kinase (PI3K) activity was found to be significantly enriched in T2DM, and reduced activity of PI3K, a key enzyme in insulin signaling, may lead to insulin resistance and elevated blood glucose." (PMID 40951426, 2025). "A consequence of reduced insulin in the brain could result in decreased neuronal insulin signaling and/or brain insulin resistance that exacerbate cognition." (PMID 39421964, 2025). "Also, the liver is crucial in glucose and lipid homeostasis via hepatic insulin signaling and is usually affected by long‐term insulin resistance and hyperglycemia situations." (PMID 39803222, 2025). "Insulin resistance is defined as a state of decreased responsiveness of target tissues to insulin." (PMID 39992249, 2025). "For instance, insulin resistance might alter leptin signaling within a hypothalamic cell line, and leptin resistance could lead to the suppression of insulin signaling." (PMID 40283443, 2025). "Taken together, the intermediate state with high BMI and relatively low PG and HbA1c levels may correspond to a state with mild insulin resistance before reaching the maximum capacity of insulin secretion." (PMID 40395818, 2025). "Whereas type 1 diabetes (T1D) is characterized by an autoimmune response involving autoantibodies against insulin-producing beta cells, type 2 diabetes (T2D) and gestational diabetes mellitus (GDM) are linked to insulin resistance and low-grade inflammation, influencing the maternal metabolic state." (PMID 40597162, 2025). "Previous research suggests that postprandial hyperglycemia arises from progressive β-cell dysfunction and peripheral insulin resistance, often attributed to oxidative stress-induced decompensation of pancreatic islet function and disruption of insulin signaling pathways during pregnancy." (PMID 41590635, 2025). "Furthermore, KEGG enrichment analysis indicated that CRRDEGs were primarily enriched in signaling pathways such as Insulin signaling pathway, Endocytosis and Insulin resistance." (PMID 40642528, 2025). "Insulin resistance (IR) can be defined as an insufficient tissue response to insulin signaling." (PMID 39941639, 2025). "These cytokines can interfere with insulin signaling pathways, leading to insulin resistance." (PMID 41141352, 2025). "However, in GDM pregnancies, the high insulin resistance, decreased insulin sensitivity, and impaired β-cell secretion lead to high levels of blood glucose." (PMID 40225013, 2025).
Insulin resistance (continued). "In contrast, type 2 diabetes (T2D) is a multifactorial and heterogeneous metabolic condition, the pathogenesis of which is frequently attributed to a complex interplay of obesity, insulin resistance (IR), and β-cell dysfunction, leading to a decline in insulin secretion and/or insulin sensitivity." (PMID 41425544, 2025). "Additionally, tumour necrosis factor-α (TNF-α) is secreted from macrophages and impairs insulin signalling, leading to insulin resistance." (PMID 39803918, 2025). "In addition to restoring GSH levels and reducing oxidative stress and inflammation, GlyNAC significantly lowered insulin resistance and fasting insulin." (PMID 41149623, 2025). "This helps to improve insulin signalling and reduce the occurrence of insulin resistance." (PMID 40878475, 2025). "They suggested that the presence of androgen receptors in liver cells may allow excess androgens to stimulate the overproduction of fetuin-A and insulin, potentially contributing to insulin resistance." (PMID 40529825, 2025). "AAL improved insulin resistance, as indicated by enhanced insulin levels and OGTT results." (PMID 41029678, 2025). "The findings suggest that a higher GRS is linked to lower insulin secretion rather than increased insulin resistance." (PMID 39902403, 2025). "The administration of metformin produces beneficial effects for patients with type 1 diabetes features and insulin resistance because it boosts glucose uptake, along with decreased hepatic glucose production, which helps lower insulin needs and enhances metabolic measurements." (PMID 40225541, 2025). "Conversely, elevated insulin levels resulting from hyperglycemia or insulin resistance may activate growth-promoting pathways such as PI3K/AKT, thereby counteracting metformin’s inhibitory effects on cancer cells." (PMID 40678416, 2025). "Moreover, oxidative stress exacerbates insulin resistance through the activation of serine kinases that impair insulin signaling and damage β-cells, while also modulating enzymes such as cytochrome P450 17α-hydroxylase (CYP17A1) to promote hyperandrogenism." (PMID 40694958, 2025). "Additionally, these pro-inflammatory mediators can impair the activation of insulin signaling receptors on pancreatic β-cells, promoting the development of insulin resistance." (PMID 40862720, 2025). "Both HOMA-IR and fasting insulin levels are closely related to insulin resistance." (PMID 40362793, 2025). "This inflammatory environment disrupts insulin signaling pathways, worsening insulin resistance." (PMID 41329353, 2025). "There is, though, an established causal association of excess adiposity on basal insulin secretion rate, even in the absence of insulin resistance, with diet-restricted weight loss lowering insulin secretion rate without changing insulin sensitivity." (PMID 40502600, 2025). "Furthermore, impaired insulin signaling exacerbates insulin resistance, while impaired autophagy further aggravates mitochondrial dysfunction." (PMID 40723862, 2025). "However, chronic stress can lead to insulin resistance, where cells become less responsive to insulin—an early indicator of metabolic disorders in both humans and other species." (PMID 40646763, 2025). "Similarly, brain insulin resistance (bIR) can be defined as the failure of brain cells to respond to insulin as they normally would, resulting in impairments in synaptic, metabolic, and immune response functions." (PMID 40416375, 2025). "Insulin resistance (IR) is a condition in which insulin circulating in blood is unable to properly stimulate glucose uptake and/or use by insulin-sensitive organs and tissues, leading to a compensatory increase in production of insulin in the pancreas and glucose in the liver." (PMID 40141439, 2025). "Additionally, mTOR inhibitors further worsen insulin resistance by disrupting the insulin signaling pathways in skeletal muscle and adipose tissue." (PMID 39941214, 2025).
Insulin resistance (continued). "LP-IR detects insulin resistance even in lean individuals, thereby identifying insulin resistance independently of body mass index (BMI) and in African Americans who tend to have lower hepatic insulin sensitivity." (PMID 41156274, 2025). "Thus, the diabetogenic effects of aging are characterized by increased insulin resistance and reduced insulin secretion." (PMID 41357171, 2025). "Therefore, the activation of the PI3K/Akt pathway is crucial for insulin-mediated glucose transport and glycogen synthesis, and its impairment is a major contributor to insulin resistance." (PMID 40429763, 2025). "An alternative hypothesis is that primary beta-cell overstimulation results in insulin hypersecretion, subsequently leading to insulin resistance and, ultimately, beta-cell failure." (PMID 40568093, 2025). "Therefore, regulating calcium channels can improve insulin resistance and increase insulin secretion." (PMID 40248148, 2025). "The miR-33 family reduces insulin sensitivity, leading to the development of insulin resistance." (PMID 40217882, 2025). "The DASH diet can observably reduce fasting plasma glucose (FPG), insulin levels and homeostasis model assessment of insulin resistance (HOMA-IR), and improve quantitative insulin sensitivity check index (QUICKI), especially in people with obesity or hypertension complicated with type 2 diabetes." (PMID 41229546, 2025). "Additionally, we assessed AT insulin sensitivity using the adipose tissue insulin resistance index (adipo-IR) index, which integrates plasma free fatty acids (FFAs) and insulin." (PMID 41148235, 2025). "Furthermore, the observed positive correlations between LEP, BioLEP, and fasting insulin levels reinforce the role of leptin as a marker of insulin resistance in pediatric obesity, a relationship well documented in the literature." (PMID 40586327, 2025). "Additionally, the combination of APS with insulin has been shown to diminish the insulin resistance index by reducing TNF-α expression, which is beneficial for the management of diabetes." (PMID 40143189, 2025). "Comparative data from rodents, dogs, cats, pigs, non-human primates, and humans were analyzed to identify species-specific patterns in insulin secretion, insulin resistance (IR), β-cell dysfunction, microbiota–metabolism interactions, and susceptibility to diabetic complications." (PMID 41598218, 2025). "Our study found that the daily consumption of non-alcoholic mixed beer increased fasting glucose, and non-alcoholic wheat beer increased insulin levels, thus indicating the impairment of glucose metabolism and development of insulin resistance—a key component of metabolic syndrome and MASLD." (PMID 40431365, 2025). "Initial searches focused on “MIGRAINE AND (neurogenic inflammation)” (2019–15 April 2025), followed by expanded searches from 1950 onward using terms such as “MIGRAINE AND (insulin, insulin resistance, hyperinsulinism)”, and “MIGRAINE AND (diet, dietary, nutrition, nutritional)”." (PMID 40426647, 2025). "Furthermore, the unchanged fasting serum glucose across groups, along with increased pancreatic islet size in both casein-fed groups, reinforces the compensatory insulin hypersecretion characteristic of early-stage insulin resistance." (PMID 41156477, 2025). "The critical concepts highlighted by ongoing research reflect the dynamic nature of our understanding of MetS and evaluating individual components such as insulin resistance and impaired insulin signaling, abdominal obesity, oxidative stress, and defective mitochondrial biogenesis is important." (PMID 40696355, 2025). "Contraction-induced myokines (e.g., IL-6) can further augment insulin signaling and exert anti-inflammatory effects, which is pertinent for individuals with obesity who commonly exhibit low-grade inflammation and insulin resistance." (PMID 41356824, 2025).
Insulin resistance (continued). "It has been proposed that the rs4885322 SNP may influence UCHL3 gene expression, disrupting cellular Ub levels, which in turn could impair insulin signaling, promoting insulin resistance and hyperglycemia." (PMID 40002753, 2025). "Furthermore, the homeostatic model assessment of insulin resistance index was significantly lowered in KS-40070-treated mice, indicating improved insulin sensitivity." (PMID 40799825, 2025). "LTB4 also interferes with insulin signaling pathways, instigating insulin resistance (IR)." (PMID 39943721, 2025). "For example, women with obesity with high levels of leptin develop resistance to its effects rather than sensitivity, showing a positive correlation with serum insulin levels, insulin resistance, and liver damage, including both steatosis and inflammation, contributing to MASLD/MASH." (PMID 40299427, 2025). "Bavachin isolated from the seeds and fruits of Psoralea corylifolia L. could ameliorate glucose homeostasis and insulin sensitivity; pinocembrin (5,7-dihydroxyflavone) enhanced glucose consumption and improved insulin resistance." (PMID 40298635, 2025). "Early combinations of variables within the phenotype cluster analysis found expected concordance between insulin resistance and hypertriglyceridemia, consistent with the known anabolic actions of insulin and regulation of lipid metabolism, with inhibition of lipolysis." (PMID 41180187, 2025). "Importantly, muscle insulin resistance typically precedes liver insulin resistance, setting the stage for systemic metabolic deterioration." (PMID 40869061, 2025). "Insulin resistance, prevalent in obese individuals and those with type 2 diabetes, may result in elevated levels of insulin and insulin-like growth factors, which have mitogenic and anti-apoptotic effects on endometrial cells, further increasing cancer risk." (PMID 40149377, 2025). "This anti-inflammatory effect may improve insulin signaling pathways and reduce systemic insulin resistance." (PMID 40284166, 2025). "These hormones contribute to the physiological insulin resistance of pregnancy, a critical adaptation that increases maternal glucose availability for the fetus, while also promoting compensatory insulin secretion to maintain maternal glucose homeostasis and prevent hyperglycaemia and GDM." (PMID 40944254, 2025). "This steady release of glucose also reduces the insulin demand on the pancreas, which is especially important for individuals with type 2 diabetes, where insulin production may be impaired or insulin resistance is present." (PMID 40026940, 2025). "Insulin resistance co-occurs with hyperinsulinemia because of defective insulin action." (PMID 40549205, 2025). "Through the increased production of lipolysis and circulating levels of insulin antagonist hormones (growth hormone, cortisol and catecholamines), smoking may directly impair insulin sensitivity and lead to the development of insulin resistance." (PMID 39789419, 2025). "Both interventions yielded significant improvements in metabolic parameters, as demonstrated by decreased serum insulin, triglyceride, and total cholesterol levels, reduced homeostatic model assessment for insulin resistance (HOMA-IR), and improved glucose tolerance (all P≤0.0382)." (PMID 41624158, 2025). "Insulin resistance is defined as a condition in which there is an inability of insulin-targeted tissue to respond to normal insulin levels, and thus, higher-than-normal levels of insulin are required to maintain the normal functions of insulin." (PMID 40710038, 2025). "Previous studies have reported that IL-10 levels are negatively correlated with insulin resistance and positively correlated with insulin sensitivity, suggesting that higher IL-10 concentrations contribute to improved metabolic regulation in individuals with obesity." (PMID 41367390, 2025).